SHANK3 (SH3 and multiple ankyrin repeat domains 3)
Diseases named in the same sentence as SHANK3 in open-access papers (continued):
Sharing a sentence is not in itself a finding about the gene and the disease.
autism (continued). "The Shank3 KO animals in the present study displayed a very robust phenotype in the motor domain, but significantly more interindividual differences on tests of autism-like behavior." (PMID 36699652, 2022). "Evidence from animal models has shown that Nrxn1α, Shank3, and Nrxn2α knockout mice display autism-related behaviors, which may be explained by modifications that favor synaptic dysfunction." (PMID 34627165, 2021). "Many of these genes, including neuroligins, neurorexin 1, PTEN, PSD95, MAPK1, JAKMIP, SHANK3, and CYFIP1, are linked to autism when they are mutated, which may explain the high comorbidity that exists between FXS and ASD." (PMID 34926684, 2021). "Mutated or non-functional brain protein SHANK3 is responsible for communication problems in children with autism." (PMID 34827633, 2021). "We finally highlighted the importance of studying long-term spontaneous communication by investigating female mice lacking Shank3, a synaptic protein associated with autism." (PMID 34720899, 2021). "Although studies have shown that BTBR mice share important changes in relevant genes and proteins involved with autism, additional studies in mice carrying mutations in specific genes involved in autism (ex, CHD8, Shank3) are necessary to recognize the impact of early anesthetic exposures in NDDs." (PMID 34912193, 2021). "To explore this, we performed microendoscopic GCaMP imaging in mice lacking the autism-associated gene Shank3." (PMID 33939689, 2021). "Moreover, it is likely that the existence of a sexual dimorphism in the circadian rhythms of autism models, such as the Shank3+/– mice, awaits being addressed." (PMID 33679297, 2021). "A similar scenario has been described in studies of SHANK3-related autism." (PMID 33616084, 2021). "Interestingly, mutations in SHANK3 (a postsynaptic scaffolding protein implicated in synapse development and ASDs) have effects on the oxytocinergic system and this alteration could be the cause of some behavioral phenotypes related to synaptic plasticity in autism." (PMID 32182969, 2020). "Moreover, the relation of zinc uptake and the expression of Shank3 regarding autism has been studied recently." (PMID 32244359, 2020). "Most research on the role SHANK3 in the brain is related to autism." (PMID 31699891, 2019). "SHANK3 mutations are one of the most prevalent monogenic causes of ASD, accounting for at least 0.69% of all cases, and patients harboring SHANK3 truncating mutations display autism combined with moderate to severe intellectual disabilities." (PMID 31481894, 2019). "Genetic defects of SHANK3 (PROSAP2) are one of the most replicated findings in autism genetics." (PMID 30809159, 2019). "Notably, however, Scn2a+/- adult and juvenile mice showed increased direct social interaction, a result often observed in other mouse models of autism that lack, i.e., the excitatory postsynaptic scaffolding protein Shank3." (PMID 31249508, 2019). "Human SHANK3 mRNA shows developmentally regulated dendritic localization in hiPSC-derived neurons, which is reduced in neurons generated from a haploinsufficient individual with autism." (PMID 30064494, 2018). "In autism and also schizophrenia cases, insertions, deletions, nonsense and splice site mutations have been observed on one SHANK3 allele which lead to loss or truncation of the protein." (PMID 30131675, 2018). "First, restoring Shank3 levels in adult mice ameliorates their autism phenotype." (PMID 29875651, 2018). "An initial study analyzed the DNA methylation profile of the autism-related gene Shank3." (PMID 27462204, 2016).
autism (continued). "Among 760 ASD patients evaluated SHANK1 mutations were found in 0.04% and were present in males with normal IQ and autism, SHANK2 mutations were present in 0.17% of patients with ASD and mild intellectual disability and mutations in SHANK3 were present in 0.69% of the patients with ASD." (PMID 27458336, 2016). "Post hoc analyses showed a statistically significant decrease, such that there was a >40% reduction in the mean densities of immature DCX+ neurons in the ventral dentate gyrus in both mouse models of autism compared to wild-type mice (WT vs Cntnap2−/−, p = 0.02; WT vs Shank3+/ΔC, p = 0.02)." (PMID 27785461, 2016). "Using five autism-related mouse models, Shank3+/ΔC, Mecp2R308/Y, Cntnap2−/−, L7-Tsc1 (L7/Pcp2Cre::Tsc1flox/+), and patDp(15q11-13)/+, we report specific perturbations in delay eyeblink conditioning, a form of associative sensory learning requiring cerebellar plasticity." (PMID 26158416, 2015). "To date, published investigations have not evaluated ASD in SHANK3 deficiency using best practice recommendations, which include combining information from clinician evaluations, structured observation, and an autism-focused, structured developmental history." (PMID 23758760, 2013). "In this issue of Molecular Autism, Soorya and colleagues evaluated 32 patients with Phelan-McDermid syndrome, caused by either deletion of 22q13.33 or SHANK3 mutations, using gold-standard diagnostic assessments and showed that 84% met criteria for ASD, including 75% meeting criteria for autism." (PMID 23758743, 2013). "Interestingly, our analysis revealed a significant excess of rare, potentially deleterious variants in three known autism genes, SHANK3, TSC1, and TSC2, in individuals with non-syndromic autism." (PMID 22558107, 2012). "Although significant enrichment of rare, potentially disruptive variants in AGRE samples relative to controls was limited to the TSC1, TSC2, SHANK3, and HOMER1 genes, individual variants in additional genes suggest a role for the Ras/ERK cascade in autism susceptibility." (PMID 22558107, 2012). "Mutations in SHANK3 have previously been reported as rare monogenic cause of non-syndromic autism and syndromic autism (in the context of the 22q13.3 microdeletion syndrome)." (PMID 22558107, 2012). "Owing to its emerging role in neuropsychiatric disorders and to the phenotypic overlap between autism and PMS, SHANK3 has become a target for mutation screening in patients with autistic spectrum disorders (ASD) and several studies have discovered de novo mutations in such patients." (PMID 21779178, 2011). "In addition, SHANK3 is one of the predicted targets of dysregulated microRNA (miRNA), and altered miRNA expression levels were found in postmortem brain from autism patients." (PMID 21615902, 2011). "Several potential reasons might explain the difference among various reports about SHANK3 gene and autism." (PMID 19566951, 2009). "Our family-based association study provided an indication that SHANK3 was not critical for the pathogenesis of autism in Chinese Han population or only account for a small proportion of autism individuals." (PMID 19566951, 2009). "Based on this evidence, we hypothesized that the SHANK3 might be a strong candidate gene for autism." (PMID 19566951, 2009). "Seven SNPs in SHANK3 gene were genotyped in 305 Chinese Han autism trios." (PMID 19566951, 2009). "Their suggestion that SHANK3 deletions may be limited to a portion of autism was coincident with ours." (PMID 19566951, 2009). "Thus, it raises a possibility that the hypothalamus may be an important brain site in Shank3-related autism." (PMID 38570876, 2024). "Previous rodent studies have shown that Shank3 deletion caused abnormal behaviors relevant to ASD, including social interaction deficits and repetitive behaviors, which provide evidence supporting the face validity of Shank3 deficiency mouse as an autism model." (PMID 38297387, 2024).
autism (continued). "We hypothesize that the Trx system is altered in the Shank3 KO mouse model of autism, which may lead to a decreased activity of the nuclear factor erythroid 2-related factor 2 (Nrf2), resulting in oxidative stress, and thus, contributing to ASD-related phenotypes." (PMID 39347996, 2024). "Despite these and other possible limitations, our results demonstrate that the Shank3-InsG3680(+/+) mouse model of ASD displays auditory avoidance and points to the need for future research on auditory circuit dysfunctions associated with disorders falling within the autism spectrum." (PMID 37693284, 2023). "Thus, the construction of a autism rat model with a large fragment deletion of Shank3 may provide further information about the pathogenesis of ASD and allow for the exploration of the mechanisms of various behavioral and motor characteristics." (PMID 36221783, 2023). "Exploring the SHANK3 gene may help uncover some of the neurobiological aspects of autism." (PMID 36846568, 2023). "Autosomal dominant ID with speech impairment, hypotonia, epilepsy, autism, dysmorphic features and renal and/or structural brain abnormalities have been described in association with either intragenic variants or deletions involving the SH3 and multiple ankyrin repeat domains 3 (SHANK3) gene." (PMID 34440332, 2021). "Further studies are needed to understand if and how OT may regulate social interactions and other relevant behaviours in zebrafish mutants lacking CNTNAP2, SHANK3, and other genes contributing to the risk of autism." (PMID 32214126, 2020). "Pertinent to the microbiome involvement hypothesis, Lactobacillus reuteri, a commensal bacterial species with decreased relative abundance in the autism-lined Shank3 knockout mice microbiome, positively correlated with the expression of GABA receptor subunits in the brain." (PMID 32072336, 2020). "Therefore, USP8 and SHANK3 synergistically affect the development of autism." (PMID 32273901, 2020). "In addition, SHANK3 was identified as a major autism candidate gene." (PMID 29875651, 2018). "Based on the fact that approximately 0.7% of individuals with ASD exhibit a mutation in SHANK3, we further compared our datasets with the SFARI autism gene database to identify molecular patterns that could be of relevance for a better understanding of ASD-associated pathomechanisms in our model." (PMID 28261056, 2017). "Studies from the last decade have repeatedly outlined that genetic disruptions of SHANK3 in humans are of upmost clinical relevance as they can lead to various neuropsychiatric disorders including the PMS, a complex neurodevelopmental condition and syndromic autism variant, non-syndromic ASD and ID." (PMID 28261056, 2017). "Whether Zn therapy also is helpful in absence of Zn deficiency for PMDS or Autism patients with mutation in SHANK3 needs further investigation and new strategies for Zn delivery bypassing classical Zn uptake pathways may be required." (PMID 28345660, 2017). "Lastly, from the 150 individual evaluated there was one case (X) identified with duplication of the SHANK3 gene on 22q13.33, associated with mild autism and average intellectual quotient and without other significant neurodevelopmental alterations except for clumsiness." (PMID 28174603, 2017). "In addition, we identified a number of novel rare SHANK3 SNVs in the autism population." (PMID 22558107, 2012). "We suggest that SHANK3 might not represent a major susceptibility gene for autism in Chinese Han population." (PMID 19566951, 2009). "All these indicate that SHANK3 might be a strong candidate gene for autism." (PMID 19566951, 2009).
autism (continued). "We identified 178 phosphorylation sites with higher phosphorylation level on the left striatum and 124 on the right among 142 autism-related proteins, including ANK2, CaMK2B and SHANK3." (PMID 40890295, 2025). "Compared to an updated list of 109 genes found to be significantly dysregulated in individuals with autism from several recent ASD expression studies, merely one (SHANK3) was found to be shared with ours." (PMID 39123267, 2024). "Reduced sleep across the lifespan in Shank3 murine model parallels sleep disturbance in human PMD and autism studies." (PMID 37441676, 2023). "It has been reported that dysfunction of the somatosensory cortex leads to sensory hyper-reactivity in a Shank3 mouse model of ASD, so it is quite possible that auditory, acting as one of the sensory abilities, become more sensitive in autism patients." (PMID 35465089, 2022). "Previously developed genetic autism mouse models (SETD5, UBE3A, SHANK3, Timothy syndrome) also observed reduced neurite outgrowth, sometimes in concert with the reduced synaptic connectivity." (PMID 33727673, 2021). "Restricted and repetitive behaviors are another core feature of autism and PMS; thus, we monitored repetitive grooming behavior in Shank3 mutant mice over a 10 min period." (PMID 32327468, 2020). "Considering that social deficits are a core feature of autism and a prominent feature of PMS, we tested Shank3 mutant mice in social tasks." (PMID 32327468, 2020). "In this study, Shank3 was selected as a target gene for gene modification, and the efficacy of CRISPR/Cas9 against Shank3 was examined towards the creation of marmoset autism models via Shank3 KO." (PMID 31481684, 2019). "At the level of individual pathway genes, we identified a significant excess of SNVs in the autism population for the TSC1, TSC2, SHANK3, and HOMER1 genes (P<0.05)." (PMID 22558107, 2012). "Some autism candidate genes that have been identified so far, such as COMMD1, MTF1, MTs, ZnT5, ERK1, TrkB, Shank2, and Shank3, are influenced by Zn2+ or themselves involved in Zn2+ signaling and metal ion homeostasis." (PMID 23346059, 2012). "The identification of novel rare CNVs in autism (NRXN1, SHANK3, and CNTNAP2) and schizophrenia has generated much excitement." (PMID 21209939, 2010). "The previous evidence about SHANK3 was always from subjects with ASD, including autism, Asperger syndrome and PDD-NOS." (PMID 19566951, 2009). "A previous study on autism-associated genes did not report evidence for sex-specific expression patterns of SHANK2 and SHANK3 in the adult human CTX." (PMID 37953224, 2023). "Impairments in social interactions and communication, some of the core symptoms of autism, were not always observed in the different Shank3 mouse models." (PMID 37008785, 2023). "Taken together, there is compelling evidence, suggesting that SHANK3 haploinsufficiency is responsible for the majority of neurological features, i.e., intellectual disability and autism, but not the full spectrum of phenotypes observed in PHMDS." (PMID 33407854, 2021). "In this article, we compared autism and schizotypy-related phenotypes to SHANK3 rs9616915 SNP genotypes in a large nonclinical population." (PMID 34188957, 2021). "For example, in 2018 a study on the genetic model of Shank3 autism showed the negative effect of environmental enrichment on the anxiety and its lack of impact on social behavior." (PMID 33503967, 2021). "Interestingly, disruption of zebrafish orthologs of another autism gene, the SH3 and multiple ankyrin repeat domains 3 (SHANK3), also altered gut motility." (PMID 33553169, 2020). "Probands from two of these families carried a second rare variant in addition to the HOMER1 variant, but these other variants did not co-segregate with the autism phenotype (HOMER1 c.290C>T and SHANK3 c.898C>T; HOMER1 c.195 and PIK3CA c.2294+19C>T)." (PMID 22558107, 2012).
autism (continued). "While SHANK1 has not been associated with autism, mutations in SHANK2 and SHANK3, other members of the SHANK gene family, appear in several individuals with autism." (PMID 21695253, 2011). "In other models of autism, such as maternal high-fat diet (HFD), direct administration of L. reuteri ATCC-6475 to weanling males (P21 for 4 wk) failed to reverse repetitive behavior but was effective in adult males and females in a monogenetic Shank3 ASD model." (PMID 39520540, 2025). "MYT1L is not the only autism related gene to show differential sex effects, so similar experiments should be done in other models (Shank3, Ube3a) to determine how generalizable these gonadal and chromosomal contributions are to neurodevelopmental traits, and with updated FCG mice." (PMID 39966983, 2025). "As will be described, it is thought that SHANK3 and SYNGAP play a key role in PSD structure and function; as a result, their dysfunction, and potentially the effect of various pharmaceuticals on the PSD, may be crucial in the pathogenesis of autism." (PMID 38352654, 2024). "In addition to the symptoms of autism, genetic screening of patients with ASD who have not yet been diagnosed with PMS also revealed many SHANK3 mutations." (PMID 36846568, 2023). "Hence, the present study was designed to compare two synaptic gene conditions with high penetrance for autism; Phelan-McDermid Syndrome (PMS, also known as 22q13 deletion syndrome, typically including haploinsufficiency of the SHANK3 gene) and NRXN1 deletions (NRXN1ds)." (PMID 35250452, 2022). "These include environmental models (maternal exposure to valproic acid), genetic models (Shank3 knockout), and idiopathic models (BTBR mice show autistic traits but there are no known genetic or environmental sources, and as such these mice are considered to represent idiopathic autism)." (PMID 32383208, 2020). "The second phosphopeptide with the RPX(S/T)P motif belonged to SHANK3, a postsynaptic density protein with a role in synaptic plasticity that acts as a scaffold protein to bind NLGN-NRXN and NMDAR at the postsynaptic density and has been involved in intellectual disabilities and autism." (PMID 31803016, 2019). "Such crosstalk could also contribute to psychiatric disorders, since a Shank3 deletion mutant lacking the Homer binding site has been identified in autism." (PMID 20305784, 2010). "The present study indicates that SHANK3 may not be a critical gene for the etiology of infantile autism in Chinese Han population." (PMID 19566951, 2009). "Recently, the Autism Mouse Connectome (AMC) study compared connectivity alterations in 16 autism-related genetic and etiological models including Cntnap2 and Shank3 knockout models, but not Nrxn1." (PMID 35052369, 2021). "Two of our patients with interstitial microdeletions disrupting SHANK3 and ACR only (P38, P43) fulfill the clinical criteria for a diagnosis of autism, while the others (P37, P42, P44), do not." (PMID 21779178, 2011). "Interestingly, altered expression of ribosomal proteins has also been found in a mouse model lacking Shank3 as well as in human cell lines and brain tissue from autistic individuals, suggesting that altered ribosomal biogenesis may be a more widespread feature in autism." (PMID 35601025, 2022). "Additionally, we noted massive albeit bidirectional hippocampal changes in the autism-related transcripts of Grin2b, PTEN and SHANK3, predicting behavioral differences; but not in the inflammation-associated CHRNA7, indicating limited relevance for brain inflammation." (PMID 32503154, 2020).